SKP2 (S-phase kinase associated protein 2)
Diseases named in the same sentence as SKP2 in open-access papers (continued):
Sharing a sentence is not in itself a finding about the gene and the disease.
cancer (continued). "Other factors, such as the ubiquitin ligase, S-phase kinase-associated protein 2 (Skp2), are known to regulate p27 and have also been found to correlate with p27 expression in cancer." (PMID 20955608, 2010). "This is especially true in PTEN-deficient tumors or tumors overexpressing Her-2/neu receptors, which were found to activate this pathway and were also commonly associated with Skp2 overexpression in different cancers." (PMID 16859513, 2006). "Through mechanisms that are yet not completely understood, Skp2 is overexpressed in some cancers and is associated with poor disease free and overall survival." (PMID 16859513, 2006). "In addition, we explored the cBioport dataset for the frequencies of SKP2 genetic alterations (i.e. amplification, deep deletion, and mutation) in cancers." (PMID 41542047, 2026). "Dysregulation of SKP2 has been linked to various diseases, including cancer, where it may contribute to the altered autophagic processes that help cancer cells survive under stress." (PMID 40136667, 2025). "Indeed, the SKP2 gene is frequently mutated in human cancers, but the exact mechanism of SKP2 as an oncogene requires in-depth research." (PMID 39851497, 2025). "Overexpression of SKP2 is associated with poor prognosis in many of these cancers." (PMID 37885161, 2024). "Consequently, SKP2 plays crucial roles in cell proliferation and differentiation, and is implicated in oncogenesis due to its overexpression in human cancers." (PMID 38672640, 2024). "SKP2 has been implicated in resistance to chemotherapy, and targeting SKP2 could potentially restore the sensitivity of cancer cells to these treatments." (PMID 37885161, 2024). "Targeting SKP2 and its associated epigenetic processes may hold promise for developing novel therapeutic strategies, especially in the context of cancers where Skp2 is dysregulated and contributes to disease progression." (PMID 38559562, 2024). "Importantly, the elevated cytoplasmic Skp2 distribution is observed and associated with the progression of malignancy in several cancer types." (PMID 38561375, 2024). "Skp2 was a target for cancer treatment and was implicated in controlling CDKN1B expression." (PMID 37432583, 2023). "Notably, restoration of RhoA expression in Skp2 deficiency cancer cells fully rescues the defects in cancer cell migration and invasion." (PMID 36180910, 2022). "Finally, as SKP2 copy number losses and aberrant expression are prevalent in a myriad of cancer types, our findings likely have broad pathogenic implications beyond the CRC contexts of this study." (PMID 36496990, 2022). "Moreover, 12 inhibited the adenosine monophosphate-activated kinase (AMPK), Parkin pathway, and S-phase kinase-associated protein 2 (Skp2), leading to the mitochondria-mediated apoptosis of cancer cells." (PMID 35897965, 2022). "DTL (Denticleless E3 ubiquitin protein ligase homolog) and SKP2 (S-phase kinase-associated protein 2) could degrade cancer progression via PDCD4 ubiquitination." (PMID 33996533, 2021). "SKP2 stabilizes LKB1 via K63-linked ubiquitination that is required for the growth of cancer cell." (PMID 35006464, 2021). "In addition, Aurora A kinase inhibitor LY3295668, Aurora B kinase inhibitor AZD2811, the mitotic inhibitors Taxol and STLC, and a SKP2 inhibitor were all shown to be more selective against RB1-deficient cancer cells." (PMID 33591981, 2021).
cancer (continued). "Recently, it has been reported to be associated with drug resistance in various human cancers, which suggests that Skp2 could be a better cancer therapeutic target and may overcome drug resistance." (PMID 34068643, 2021). "Together, this suggests that using MLN4924 to inhibit SKP2 could be effective in other RB1 deficient cancers." (PMID 32123578, 2020). "In addition to the cell cycle pathway, SKP2 also participates in other cancer hallmark pathways such as FOXO, AMPK/mTOR, AKT, apoptosis and Hippo signaling pathway 15-18, 20, 21, 28-32." (PMID 32226545, 2020). "Besides, the high expression of SKP2 has been implicated as a poor prognosis indicator in several types of cancers 39-41." (PMID 32226545, 2020). "Moreover, a mesenchymal phenotype was found to be associated with characteristics of cancer stem-like cells, including a DU 145 cell phenotype that was altered after Skp2 downregulation." (PMID 30952903, 2019). "In addition, Skp2 overexpression, which was found to be associated with poor prognosis, maintains the cancer stem cell pool and increases CSC self-renewal ability in nasopharyngeal cancer." (PMID 30999935, 2019). "Given that RIBE has important implications for secondary cancer risk assessment during cancer radiotherapy, SKP2 may be a potential target for EC radiotherapy." (PMID 28178195, 2017). "Furthermore, in various human cancers the increased expression of SKP2 and reduced levels of p27Kip1 have been linked to poor prognosis." (PMID 26956626, 2016). "SKP2 is overexpressed and associated with poor prognosis in various human cancers." (PMID 27317767, 2016). "Overexpression of SKP2 has been linked with poor prognosis of many cancers." (PMID 26956626, 2016). "Therefore, the elevated Skp2 levels duo to the pRb or Pten loss were suggested to be a main contributor to tumorigenesis and cancer progression." (PMID 26497688, 2015). "As a proto-oncogene, SKP2 overexpression is frequently observed in various human cancers including PCa, and aberrant elevation of SKP2 is associated with poor prognosis of cancers." (PMID 25596733, 2015). "The expression of SKP2 has been closely associated with cancer development and metastasis." (PMID 25106448, 2014). "Another attractive E3 that could be exploited for cancer therapy is Skp2 (S-phase kinase-associated protein 2), an F-box protein that forms part of the SCF complex." (PMID 25237759, 2014). "In addition, CAPE treatment caused G1 or G2 cell cycle arrest in several cancer cells through suppression of protein level of cyclin B1, cyclin D1, cyclin E, c-Myc, S-phase kinase-associated protein 2 (Skp2), phospho-Rb, and β-catenin." (PMID 23466879, 2013). "In the vast majority of cases, SKP2 overexpression inversely correlates with p27KIP1 expression, which is consistent p27KIP1 being a key target of SKP2 and to be rarely mutated in cancer." (PMID 23226679, 2012). "The combination of AJCC staging with Skp2 expression may be useful in identifying patients with increased risk of cancer recurrence for complete resected ESCC." (PMID 22533738, 2012). "Skp2 is frequently overexpressed in a variety of cancers and associated with patient survival." (PMID 21386910, 2011). "Overexpression of Skp2 is associated with a variety of human cancers, indicating that Skp2 may contribute to the development of human cancers." (PMID 20526532, 2010). "Thus, the underlying mechanisms of SKP2 expression in cancers require further investigation." (PMID 37308972, 2023). "Thus, loss of Cdh1 cannot explain the observation of elevated Skp2 levels in carcinomas." (PMID 19549334, 2009).
cancer (continued). "In univariate analysis, low p27Kip1 expression, Skp2 and Cks1 expression were all associated with a poor prognosis, while in multivariate analysis, only low p27Kip1 expression were independent prognostic factors for both cancer specific survival and recurrence-free survival in patients with RCC." (PMID 18922157, 2008). "Therefore, p27Kip1 degradation is dependent upon the accumulation of Skp2 and Cks1 as well as the rise in cyclin E. Recently, the expression levels of p27Kip1, Skp2 and Cks1 were shown to be highly associated with prognosis in a variety of cancers." (PMID 18922157, 2008). "Taken together, these results strongly support that SKP2 plays a key role in cancer initiation and can serve as an important target for cancer chemoprevention." (PMID 41542047, 2026). "Genetic inactivation of SKP2 has been shown to effectively prevent cancer initiation and block tumorigenesis." (PMID 41542047, 2026). "More interestingly, this cancer-derived mutant c-Myc displayed more oncogenic activity than did wild type c-Myc in vitro and in vivo, in part, by partnering with Skp2." (PMID 42224600, 2026). "Curcumol, a sesquiterpene natural product, has been reported to regulate SKP2-mediated ubiquitination degradation to overcome drug resistance in cancer cells." (PMID 41900096, 2026). "We have also shown that genetic and pharmacological depletion of SKP2 reduces tumor-initiating properties and cancer stemness." (PMID 41542047, 2026). "Knockdown of YAP significantly decreased the sensitivity to lipid peroxidation and ferroptosis, while genetic or chemical inhibition of SKP2 protected cancer cells from ferroptosis." (PMID 40539051, 2025). "In another study, it is found that the long non-coding RNA Meg3 enhances miR-3163-mediated suppression of Skp2 protein translation, inhibiting cancer cell growth in NSCLC." (PMID 40396180, 2025). "Several other studies demonstrate the validity of targeting SKP2 in other forms of cancer, including leukemia." (PMID 39851497, 2025). "For instance, it is reported that Skp2 inhibitor C1 (SKPin C1) potently suppresses the growth of several cancers." (PMID 41385185, 2025). "This discovery reveals the critical regulatory roles of YAP and SKP2 in ferroptosis and offers new therapeutic avenues for targeting YAP or SKP2 in cancer treatment." (PMID 40539051, 2025). "F-Box protein FBXW2 induces S-phase kinase-associated protein 2 (SKP2), a newly identified tumor suppressor in various cancers." (PMID 39261475, 2024). "Our findings unveil a new role of RCC1 in promoting the nucleo-cytoplasmic trafficking of oncogenic Skp2 protein, the process of which is commonly observed and correlated with the progression of many types of cancer." (PMID 38561375, 2024). "The Skp2 gene promoter is reported to be hypermethylated in some cancer types, decreasing SKP2 expression." (PMID 38559562, 2024). "Further, we performed a limited in-silico analysis to establish the involvement of SKP2 in a few publicly available cancer datasets." (PMID 38559562, 2024). "Epigenetic regulation of Skp2 is particularly relevant in cancer, where dysregulated Skp2 expression can contribute to uncontrolled cell proliferation and tumorigenesis." (PMID 38559562, 2024). "It was reported that SKP2 is a well‐characterized cancer‐related protein, whose stability was regulated by ubiquitin-proteasome system (UPS) during the cell cycle." (PMID 39438468, 2024). "Mainly through PI3-kinase signaling, the mTORC2 pathway elevates the Skp2 expression, thereby reducing the p27 expression and initiating cancer progression." (PMID 38559562, 2024). "Understanding the role of SKP2 in immune evasion is crucial for developing strategies to enhance immune responses against cancer cells and improve the efficacy of immunotherapies." (PMID 38559562, 2024).
cancer (continued). "Taken together, our results raise the possibility that adding SKP2 inhibitors into the current chemo regimen for OS can improve outcomes by targeting the cancer stem cell population and reducing chemoresistance in OS." (PMID 38355807, 2024). "The degradation of p27 in cancer is usually mediated by SKP2-mediated proteolysis in addition to mRNA expression-based mechanisms, including miRNA." (PMID 38725021, 2024). "In this study, we confirmed that AAA237 binds to Skp2 biophysically and further investigated the anti-cancer effect of AAA237 in vitro, showing that it inhibited the proliferation, migration and invasion of human GBM cells." (PMID 38341584, 2024). "Changes in miRNA expression profiles in cancer or other diseases can influence Skp2 expression through post-transcriptional regulation." (PMID 38559562, 2024). "Understanding the interplay between SKP2 and epigenetics is critical for unraveling the complexities of cancer biology and other diseases." (PMID 38559562, 2024). "Reduced Skp2 expression due to DNA methylation can contribute to cell cycle dysregulation and impact cancer progression." (PMID 38559562, 2024). "There was a significant inverse correlation between p27 expression in cancer cells and Ki-67 and SKP2 expression (p < 0.001 and p = 0.030, respectively)." (PMID 38725021, 2024). "Using the DKOAA transgenic model, we recently showed that the binding between Skp2 and p27 likely enhances OS cancer stemness." (PMID 38355807, 2024). "Skp2’s overexpression exhibits an oncogenic property that shields cancer cells from apoptosis, even in the face of DNA damage." (PMID 38724504, 2024). "SKP2 can also promote immune evasion in cancer by regulating immune checkpoint molecules, immune response pathways, Treg function, antigen presentation, and the overall immune microenvironment." (PMID 38559562, 2024). "Numerous studies have shown that SKP2 is overexpressed in many human cancers, including prostate, breast, lung, colorectal, and gastric cancers, as well as lymphomas, melanomas, and sarcomas." (PMID 37885161, 2024). "While it was found to be overexpressed in several cancer types, few cancer showed a down-regulation in SKP2." (PMID 38559562, 2024). "SKP2 can influence the epithelial–mesenchymal transition, a process through which cancer cells acquire invasive and metastatic properties." (PMID 37885161, 2024). "Supporting this, analysis of the Cancer Genome Atlas database reveals a close association between EZH2 and SKP2 expression in human malignancies." (PMID 38862595, 2024). "Understanding the epigenetic modifications that affect SKP2 and their functional consequences is essential for developing targeted therapies that can restore normal SKP2 regulation in cancer cells." (PMID 38559562, 2024). "SKP2-mediated p27Kip1 dysregulation has been observed in many types of cancers, and proteasome inhibitor BTZ reduces the expression of Skp2 in CML." (PMID 38559562, 2024). "Based on several reports, downregulation of Skp2 induces the p27, promotes apoptosis, and sensitizes different types of cancers." (PMID 38559562, 2024). "Additionally, SKP2 was found to be associated with specific signaling pathways (e.g., “complement and coagulation cascades,” “cytokine–cytokine receptor interaction,” and “metabolism of xenobiotics by cytochrome P450”) in at least two cancers, which required further experimental investigation." (PMID 37308972, 2023). "Previous studies showed that FBXW2 functions as putative tumor suppressor in many cancers through directing proteasomal degradation of several oncogenes including SKP2, β-catenin, and EGFR." (PMID 37736741, 2023). "Although the efficacy of these compounds for human cancer needs to be further justified, Skp2 is still an attractive target for cancer therapy." (PMID 37532777, 2023).
cancer (continued). "S-phase kinase-associated protein 2 (Skp2), a component of the E3 ubiquitin ligase SKP1-cullin-F-box (SCF), is well known as an essential regulator of cell-cycle progression and cancer development." (PMID 36302650, 2023). "In other aspects, the CRISPR data from DepMap Portal confirmed the essential cancer role of SKP2 in certain tumors (BLCA, etc.), suggesting that SKP2 promotes cancer in these tumors." (PMID 37308972, 2023). "S-phase kinase-associated protein 2 (SKP2), also known as p45, is involved in cancer progression, migration, and invasion." (PMID 37679418, 2023). "As noted, the SCF family, which includes FBXW7, SKP2, and β-TrCP, affects various proteins that regulate overall cancer development, which makes it an attractive target to combat cancer." (PMID 37176148, 2023). "Such a result suggests that SKP2 is a potential biomarker for predicting cancer status in multiple tumors." (PMID 37308972, 2023). "Due to its close relation with cancers, Skp2 was regarded as an attractive target for cancer therapy." (PMID 37089937, 2023). "Based on the AUC analysis of the current study, SKP2 is a remarkable molecule to distinguish cancer tissues and normal tissues for various cancers (particularly BLCA, CESC, COAD, ESCA, GBM, LUSC, PCPG, and READ)." (PMID 37308972, 2023). "Selective SKP2 inhibitors with different mechanisms of action have shown anti-cancer effects in vitro and in preclinical models." (PMID 38102140, 2023). "So, when treated with MS that induce cancer cell death, the expression of Skp2 decreases simultaneously with c-Myc." (PMID 37550432, 2023). "Consistently, one study shows that a small molecule (compound SZL-P1-41) that binds to Skp2 and prevents its binding with Skp1 disrupts Skp2 E3-ligase activity toward Akt, leading to the suppression of cancer progression in mouse models." (PMID 36769122, 2023). "We report that RMS primary samples show higher SKP2 levels than normal skeletal muscle tissue and the highest among all the interrogated adult and pediatric cancers." (PMID 38102140, 2023). "Jude Children’s Research Hospital’s PeCan Data Portal showed that SKP2 expression in RMS patients had the highest levels among about 2500 pediatric cancers." (PMID 38102140, 2023). "At the same time, it is also necessary to further study the molecular mechanism of SKP2 in specific cancers." (PMID 37308972, 2023). "By inhibiting Skp2, miR-3163 increases the stability of p27 and slows the development of cancer cells." (PMID 37240281, 2023). "Accordingly, Skp2 is regarded as an oncogene and has remained a highly active topic in cancer-therapy research since its discovery." (PMID 37089937, 2023). "Public datasets also revealed a significant up‐regulation in SKP2 expression when comparing cancer recurrence in PCa patients (P = 0.0459)." (PMID 37491794, 2023). "As a ubiquitin ligase subunit, SKP2 can target to degrade CDKN1B, promote the transformation of cells from the G1 phase to the S phase, and then cause the growth and proliferation of cancer cells; this is considered the typical function of SKP2." (PMID 37308972, 2023). "SKP2 is also considered an oncogene since SKP2 is found to be overexpressed in various cancer cells." (PMID 37894498, 2023). "A significantly positive correlation between SKP2 expression and the expression levels of three DNMTs and five MMRGs was detected in almost all the 33 cancers analyzed." (PMID 37308972, 2023). "A possible example is Skp2 inhibitors, which are an active area of research in cancer therapeutics and should be evaluated for anti-HIV activity." (PMID 37766341, 2023).